AIRIM (AFG2 interacting ribosome maturation factor)
Description:
Part of the 55LCC heterohexameric ATPase complex which is chromatin-associated and promotes replisome proteostasis to maintain replication fork progression and genome stability. Required for replication fork progression, sister chromatid cohesion, and chromosome stability. The ATPase activity is specifically enhanced by replication fork DNA and is coupled to cysteine protease-dependent cleavage of replisome substrates in response to replication fork damage. Uses ATPase activity to process replisome substrates in S-phase, facilitating their proteolytic turnover from chromatin to ensure DNA replication and mitotic fidelity. Involved in the cytoplasmic maturation steps of pre-60S ribosomal particles by promoting the release of shuttling protein RSL24D1/RLP24 from the pre-ribosomal particles.
Synonyms: C1orf109; FLJ20508
Tractability: PROTAC: ubiquitination databases record sites on it.
Gene: Protein-coding gene on chromosome 1 (37,681,570 to 37,692,296, reverse strand). Ensembl gene ENSG00000116922.
Subcellular location: Nucleus; Cytoplasm
Subcellular location (Human Protein Atlas): Cytosol; Nucleoli; Nucleoplasm
Gene Ontology:
Molecular function: protein binding
Biological process: DNA replication; regulation of ribosome biogenesis; ribosomal large subunit biogenesis
Cellular component: ATPase complex; cytoplasm; cytosol; nucleolus; nucleoplasm; nucleus
Genetic constraint (gnomAD): Loss-of-function variants: 19 observed, 27.92 expected, observed/expected ratio (o/e) 0.68, 90% interval 0.47 to 1. The upper end of that interval is the gene's LOEUF score, 1, which puts it in group 4 of 6, group 1 being the genes least tolerant of losing a copy. Missense variants: 237 observed, 259.86 expected, observed/expected ratio (o/e) 0.91, 90% interval 0.82 to 1.02. Synonymous variants: 96 observed, 108.36 expected, observed/expected ratio (o/e) 0.89, 90% interval 0.75 to 1.05.
Homologues: Orthologues: chimpanzee AIRIM (99% identical), macaque AIRIM (96% identical), guinea pig AIRIM (86% identical), pig AIRIM (83% identical), rat Airim (80% identical), mouse Airim (79% identical), dog AIRIM (78% identical), tropical clawed frog airim (44% identical), zebrafish airim (36% identical).
Diseases named in the same sentence as AIRIM in open-access papers:
AIRIM is named in the same sentence as 5 diseases in open-access papers, as found by Europe PMC text mining. Sharing a sentence is not in itself a finding about the gene and the disease. The quoted sentences say what the papers report.
neurodevelopmental disorder (1 paper, 2025). A behavioral and cognitive disorder with onset during the developmental period that involves impaired or aberrant development of intellectual, motor, or social functions. "Here we describe variants in the ribosome biogenesis factor AIRIM/C1orf109 that are primarily associated with neurodevelopmental disorders." (PMID 40760247, 2025).
AIRIM also shares sentences with these, for which no sentence is quoted: cancer (3 papers); microcephaly (2); developmental delay (1); ovarian carcinoma (1).